TFF3 (trefoil factor 3)
Diseases named in the same sentence as TFF3 in open-access papers (continued):
Sharing a sentence is not in itself a finding about the gene and the disease.
breast carcinoma (continued). "A novel small molecule TFF3 inhibitor eradicated the trastuzumab resistant HER2+/ER+ breast cancer cells, without the need for trastuzumab re-sensitization." (PMID 29088778, 2017). "In addition, our observation of TFF3-mediated activation of cSRC, STAT3 and p65 (subunit of NFκB) in HER2+/ER+ breast cancer cells is consistent with published literature." (PMID 29088778, 2017). "To date, no clinical study has evaluated the expression of TFF3 in HER2+/ER+ breast cancers which have progressed on trastuzumab." (PMID 29088778, 2017). "Serum concentrations of TFF1 and TFF3 but not TFF2 are higher in women with breast cancer than in women without breast cancer." (PMID 28687783, 2017). "Hence, we propose TFF3 as a potential biomarker and therapeutic target in trastuzumab resistant HER2+/ER+ breast cancer." (PMID 29088778, 2017). "Collectively, TFF3 may function as a potential biomarker and therapeutic target in trastuzumab resistant HER2+/ER+ breast cancer." (PMID 29088778, 2017). "0.72, and the order of accuracy for breast cancer patient screening was TFF2, TFF3 and TFF1." (PMID 28687783, 2017). "As tamoxifen and trastuzumab were shown to exhibit a synergistic effect in inhibiting the growth of BT474 cells, we further examined the effect of AMPC inhibition of TFF3 in modulating response towards the combination of trastuzumab and tamoxifen in HER2+/ER+ breast cancer cells." (PMID 29088778, 2017). "In addition, our previous study has shown that TFF3 promotes STAT3-dependent transcription of IL8, thereby stimulating angiogenesis in mammary carcinoma through the IL-8/CXCR2 axis." (PMID 29100386, 2017). "Nevertheless, trastuzumab resistant HER2+/ER+ breast cancer cells, which have lost HER2 expression but exhibited upregulated TFF3, could potentially be targeted by TFF3 inhibition in vivo." (PMID 29088778, 2017). "The combination of trastuzumab and tamoxifen treatment markedly decreased the 3D matrigel growth of the HER2+/ER+ breast cancer cells, while the AMPC inhibition of TFF3 could further decrease the 3D matrigel growth of these treated cells." (PMID 29088778, 2017). "The functional role of TFF3 in de novo angiogenesis in mammary carcinoma has not yet been determined." (PMID 26559818, 2015). "To evaluate the potential of TFF3 as a predictive biomarker of response to endocrine therapy, we identified a cohort of advanced breast cancer patients who had received endocrine therapy without stratification." (PMID 25900183, 2015). "Again, TFF3 has been reported to promote motility in a range of different cell types including Madin-Darby canine kidney cells (MDCK), rat fibroblastic cells, normal and transformed bronchial epithelial cells colonic and mammary carcinoma cells." (PMID 26559818, 2015). "Expression microarray analysis, which demonstrated consistent regulation of TFF1 and TFF3 but not TFF2 in three oestrogen-responsive breast cancer cell lines, was validated by real-time RT-PCR." (PMID 25900183, 2015). "TFF1 and TFF3 mRNAs were induced by oestrogen in five oestrogen-responsive but not in two oestrogen-nonresponsive breast cancer cell lines." (PMID 25900183, 2015). "Elevated TFF3 expression has also been reported in the molecular apocrine subtype of estrogen receptor negative (ER-) mammary carcinoma under androgen control." (PMID 26559818, 2015). "Moreover, there was a significant co-expression of TFF3 with antiapoptotic proteins AKT1 (p = 0.0365), BCl2 (p = 0.0152), and NF Kappa-B (p = 0.0243) in breast carcinoma cases with residual carcinoma following neoadjuvant therapy, which reinforces the role of TFF3 in chemoresistance." (PMID 38001658, 2023). "According to the literature, TFF3 acts as an oncogene because it regulates other genes (FOXA1, HER2, and AR) involved in EMT, thus promoting invasiveness, survival, and increased proliferation in multiple carcinomas such as gastric cancer, mammary carcinoma, and prostate cancer." (PMID 37900178, 2023).
breast carcinoma (continued). "However, there was no co-relation between TFF1, TFF2, and TFF3 expression and ER in breast cancer tissue in this patients’ series." (PMID 28687783, 2017). "Because the importance of the regulation of TFF3 by oestrogen in breast cancer is unknown, unlike that of TFF1, it was studied further." (PMID 25900183, 2015). "Hence, AMPC inhibition of TFF3 has the added advantage of abrogating the remaining low level of HER signalling in the trastuzumab resistant HER2+/ER+ breast cancer cells such that eradication of these resistant cells did not require re-sensitization to trastuzumab." (PMID 29088778, 2017). "However, we could not detect a significant difference of serum TFF3 value between patients with histologically TFF3 positive breast cancer and patients with histologically TFF3 negative breast cancer." (PMID 28687783, 2017). "In the past, TFF3 - and TFF1, but not TFF2 - mRNA was detected in breast tumors and estrogen-responsive breast cancer cell lines and TFF3 was ranked among genes down-regulated in MDA-MB-231 compared to MCF7 cells." (PMID 35216615, 2022). "This further reinforces the importance of therapeutic TFF3 inhibition, which can eradicate the trastuzumab resistant HER2+/ER+ breast cancer cells alone without the need for trastuzumab re-sensitization." (PMID 29088778, 2017).
gastric cancer (34 papers, 2012 to 2025). A primary or metastatic malignant neoplasm involving the stomach. "The genes CLDN3, ADH4, and TFF3 have all been implicated in the development of gastric cancer." (PMID 37153834, 2023). "NHPH could be one of the causes for gastric cancer in Korea and partially explain differences between serum TFF3 and ABCD classifications between Korea and Japan." (PMID 35314746, 2022). "Studies have shown high serum TFF3 levels to have a sensitivity of 80.9% and specificity of 81% for gastric cancer." (PMID 36428707, 2022). "The roles of TFF3 in promoting tumor progression were also well established in breast, cervical, hepatocellular, and gastric cancers and glioblastoma." (PMID 35626334, 2022). "The TFF3 gene has been shown to be an estrogen-regulated oncogene with prognostic value in estrogen-positive breast cancer and important contributor to gastric cancer progression." (PMID 36818673, 2022). "We have previously shown that Trefoil Factor Family 3 (TFF3), a small peptide of 12–20 kD with a trefoil motif, which is secreted from various mucus-secreting cells, is an effective serum biomarker for gastric cancer both in Japan and in South Korea12." (PMID 35314746, 2022). "The number of microvessels in breast and gastric cancer correlates significantly with Tff3 expression." (PMID 31635131, 2019). "Serum TFF3 was shown to be a better potential screening tool for gastric cancer than pepsinogen in Japan." (PMID 29977284, 2018). "The mean serum TFF3 level in the patients with gastric cancer was 9.37 ± 4.67 ng/mL, which was significantly higher compared with that in the control group (7.05 ± 3.28 ng/mL; P < 0.001)." (PMID 29977284, 2018). "The mean serum TFF3 level in patients with gastric cancer was 9.01 ± 4.21 ng/mL, which was significantly higher than that in the control group (6.92 ± 2.76 ng/mL; P < 0.001)." (PMID 29977284, 2018). "The combination of serum TFF3 and pepsinogen is a more effective noninvasive biomarker for gastric cancer detection compared with pepsinogen or TFF3 alone, even in EGC." (PMID 29977284, 2018). "With combination testing, the sensitivity for gastric cancer presence was 87.5%, which was higher than that of TFF3 testing alone." (PMID 29977284, 2018). "In contrast, the depletion of TFF3 has previously been shown to enhance the sensitivity of gastric cancer cells to chemotherapeutics, in particular doxorubicin." (PMID 28445151, 2017). "Furthermore, in gastric cancer, high TFF3 protein levels have been associated with reduced overall survival only in lymph-node positive and highly undifferentiated tumors, suggesting that high TFF3 protein levels are associated with aggressiveness specifically in advanced gastric cancer." (PMID 28930171, 2017). "ROC curve analysis showed that urine TFF3 had 73.91% of positive predictive value, 80.4% sensitivity and 80.1% specificity, with an AUC of 0.874 and optimal cut-off (3.12 ng/ml) when gastric cancer patients were separated from healthy individuals." (PMID 25031551, 2014). "In contrast to gastric cancer, the serum TFF3 levels of older patients (age >60 y) with colorectal cancer were higher than the levels of younger patients (age ≤60 y, P < 0.05)." (PMID 25031551, 2014). "In previous study, a serum TFF3 level greater than 7 ng/ml indicated higher sensitivity in predicting the presence of gastric cancer." (PMID 25031551, 2014). "TFF3 also had a significantly higher predictive power for distinguishing gastric cancer than the PG test (odds ratio: 10.33 vs 2.57)." (PMID 24720760, 2014). "Real-Time PCR and western blot showed increasing of HIF-1α in mRNA and protein levels as well as TIMP1, TFF3 in mRNA levels in gastric cancer tissues." (PMID 24927122, 2014). "ROC curve analysis showed that serum TFF3 had 80.0% of positive predictive value, 80% sensitivity and 72.4% specificity, with an AUC of 0.844 and optimal cut-off (8.98 ng/ml) when gastric cancer patients were separated from healthy individuals." (PMID 25031551, 2014).
gastric cancer (continued). "To define the prognostic value of serum TFF3 levels in gastric cancer, we analyzed the clinicopathological parameters of gastric cancer." (PMID 25031551, 2014). "The serum TFF3 levels in the patients with gastric cancer were 16.59 ± 1.958 ng/ml, and were significantly elevated compared with 7.80 ± 0.233 ng/ml in the group of healthy individuals (P < 0.05)." (PMID 25031551, 2014). "The AUC for HP positive gastric cancer patients were significantly larger for TFF3 (0.83, 95% CI [0.73, 0.94]) and PG I/II ratio (0.86, 95% CI [0.74, 0.98]) than those for either TFF1 or TFF2." (PMID 24720760, 2014). "We found that serum concentrations of TFF2 and TFF3 in patients with intestinal type gastric cancer were lower than those in patients with diffuse type." (PMID 24720760, 2014). "Third, the serum TFF3 level has an association with the differentiation type and TNM stage in gastric cancer." (PMID 24720760, 2014). "To determine the prognostic value of serum TFF3 levels in colorectal cancer, we analyzed the clinicopathological parameters of gastric cancer." (PMID 25031551, 2014). "The mean TFF3 serum level in gastric cancer patients was also significantly higher than those in the other groups." (PMID 24720760, 2014). "We also evaluated the relationship between TFF3 and the histological type and stage in gastric cancer." (PMID 24720760, 2014). "The serum concentrations of TFF1, TFF2, and TFF3 in the control groups were significantly lower than those in the gastric cancer group with the exception of TFF2 which was elevated in CAG." (PMID 24720760, 2014). "The urine TFF3 levels in the patients with gastric cancer were significantly elevated to 6.46 ± 1.046 ng/ml, compared with 1.83 ± 0.162 ng/ml in the group of healthy individuals (P < 0.05)." (PMID 25031551, 2014). "We next analyzed the accuracy of using both the concentration of TFF3 and the PG test for detection of gastric cancer." (PMID 24720760, 2014). "Recently, it has been reported that serum levels of TFF3 are a better marker of gastric cancer than pepsinogen." (PMID 22246423, 2012). "Moreover, a low expression of TFF2 and TFF3, which were predicted to be inhibited by GALNT6, have been reported to associate with gastric cancer." (PMID 36748835, 2023). "However, serum TFF3 in Japanese Group A gastric cancer patients was lower than in Japanese Group B, C, and D patients." (PMID 35314746, 2022). "In addition, over-expression of TFF3 facilitated the doxorubicin resistance in gastric cancer and HCC cells, which limited the efficacy of chemotherapeutic treatment of HCC." (PMID 30424721, 2018). "Recent data indicate that serum TFFs, especially TFF3, could be potential biomarkers for the detection of gastric cancer." (PMID 29977284, 2018). "We aimed to investigate whether the combination of TFF3 and pepsinogen could be an effective biomarker for the detection of gastric cancer even in the early stages." (PMID 29977284, 2018). "The authors suggested that serum TFF3 could be a stable biomarker of gastric cancer even after H. pylori eradication in contrast with the pepsinogen test." (PMID 29977284, 2018). "Positive results of the combination of serum TFF3 and pepsinogen for gastric cancer could be helpful to encourage patients to undergo the EGD." (PMID 29977284, 2018). "It has been reported that the combination of serum TFF3 and pepsinogen testing could be a biomarker for early detection of gastric cancer." (PMID 29100347, 2017). "In line with this, elevated levels of TFF3 are seen in prostrate, colon and gastric cancers." (PMID 26083576, 2015). "Serum TFF3 may be a better predictor of gastric cancer than the PG test, while the combined testing of serum PG and TFF3 could further improve the efficacy of gastric cancer screening." (PMID 24720760, 2014). "Moreover, combining the serum TFF3 and PG tests for gastric cancer had better predictive power than either alone." (PMID 24720760, 2014).
gastric cancer (continued). "Interestingly, decreased serum TFF3 levels were significantly correlated with responses to chemotherapy in the gastric cancer PR group (P < 0.05)." (PMID 25031551, 2014). "We found the firstly, the concentration of serum TFF3 may be a better biomarker of gastric cancer than the PG test." (PMID 24720760, 2014). "Several earlier clinical studies identified serum TFF3 as a new marker for gastric cancer." (PMID 25031551, 2014). "Second, combination testing of serum PG and TFF3 could improve the efficacy of gastric cancer screening." (PMID 24720760, 2014). "Our findings therefore support serum TFF3 concentration as biomarker for gastric cancer screening." (PMID 24720760, 2014). "Furthermore, as TFF3 promotes tumorigenesis by increasing cell invasion and metastasis, gastric carcinoma patients with positive expression of TFF3 show invasive characteristics and poor prognosis." (PMID 24765170, 2014). "Therefore, the Cytosponge-TFF3 procedure had a positive predictive value of 59% (131 of 221 confirmatory endoscopies in patients with a positive Cytosponge-TFF3 result) for Barrett's oesophagus, dysplasia, or oesophago-gastric cancer." (PMID 32738955, 2020). "Because TFF3 is strongly expressed by goblet cells in the epithelium of intestinal metaplasia of the stomach (according to the histopathogenesis of gastric cancer), a high TFF3 serum level would be expected in intestinal-type and differentiated-type gastric cancers." (PMID 29977284, 2018). "We reported that serum TFF1, TFF2, and TFF3 could be good biomarkers for gastric cancer screening." (PMID 28687783, 2017). "However, when the serum TFF3 test was added, 54 of the 72 gastric cancer patients with gastric cancer were detected, that is, an additional 30 patients with gastric cancer who were not identified by the PG test alone were picked up by the serum TFF3 test." (PMID 24720760, 2014). "However, according to the histopathogenesis of gastric cancer, because TFF3 is strongly expressed by goblet cells in the normal intestine and in the intestinal metaplastic epithelium of the stomach, high expression of TFF3 would be expected in differential type and intestinal type gastric cancer." (PMID 24720760, 2014). "Many single biomarkers such as MTA1, TFF3, and CA72-4 were also reported to be related to the prognosis of gastric cancer with systemic therapy." (PMID 34245559, 2021). "TFF3 has previously been reported to induce tyrosine phosphorylation and activation of EGFR and HER2 in a colonic epithelial cell line (HT-29), gastric cancer cell line (AGS) and oral keratinocytes." (PMID 29088778, 2017). "It has been reported that TFF3 regulates the expression of VEGF and HIF-1α induced by hypoxia, in gastric cancer cell lines." (PMID 29100347, 2017). "The expression of the intestinal mucosal markers MUC13, TFF3, SPINK4, FABP1, and REG4 were increased in the GC type 1 subclass, while, the expression of the previously identified gastric cancer marker gene KRT7 was increased significantly in the GC type 2 subclass." (PMID 35785171, 2022). "Despite these promising results, currently there are no studies evaluating the utility of TFF3 for gastric cancer screening and diagnosis in clinical practice." (PMID 36428707, 2022). "Korean early gastric cancer patients of Group A, negative for Pepsinogen test and low serum H. pylori IgG, have higher serum TFF3 than Group B, C, and D patients, who are positive for either the Pepsinogen test or H. pylori IgG." (PMID 35314746, 2022). "Although the mechanism of elevated serum TFF3 in cancer patients is not known, this biomarker showed a different behavior in Japanese and Korean gastric cancer patients." (PMID 35314746, 2022). "In the intervention group, two participants who did not undergo the Cytosponge-TFF3 test were diagnosed with stage IV oesophago-gastric cancer." (PMID 32738955, 2020). "There is no previous study on serum TFF3 as a biomarker in EGC population without advanced gastric cancer (AGC)." (PMID 29977284, 2018).
gastric cancer (continued). "Our results showed that 44% of gastric carcinomas expressed TFF3, and more importantly that TFF3 over-expression in GC was an independent negative prognostic indicator for OS." (PMID 24358147, 2013). "Further large studies are required to confirm the strong predictive power of serum TFF3 and the combination tests with TFF3 and pepsinogen in patients with AGC or EGC, as well as to clarify the role of serum TFF3 as a nonendoscopic biomarker in population-based screening for gastric cancer." (PMID 29977284, 2018). "We found that 48 (66.7%) of the 72 patients with gastric cancer were negative for the pepsinogen test, while the serum TFF3 test identified an additional 30, the sensitivity of combining the results of serum TFF3 and pepsinogen tests was 75%, which was better than that of either tests alone." (PMID 24720760, 2014). "TFF3 has also been shown to induce phosphorylation of epidermal growth factor receptor (EGFR), which may in turn activate the cell survival signaling molecules PI3K and Akt in a colonic epithelial cell line (HT-29) and a gastric cancer cell line (AGS)." (PMID 24204940, 2013). "Among the 19 uniquely identified genes, 7 (GSPT1, TFF3, KLF4, ITK, GNB2L1, FLI1, and GNG5) were not included in the KEGG gastric cancer pathway, indicating that they have not been previously recognized as canonical GAC-related genes." (PMID 41284725, 2025). "Thus, elevated serum TFF3 levels may not be specific for gastric cancer." (PMID 24720760, 2014). "However, when serum TFF3 testing was added to the gastric cancer screening, 135 of the 170 EGC patients who were not identified by pepsinogen testing could be identified by the TFF3 examination." (PMID 29977284, 2018).